NBR1 (NBR1 autophagy cargo receptor)
Description:
Ubiquitin-binding autophagy adapter that participates in different processes including host defense or intracellular homeostasis. Possesses a double function during the selective autophagy by acting as a shuttle bringing ubiquitinated proteins to autophagosomes and also by participating in the formation of protein aggregates. Plays a role in the regulation of the innate immune response by modulating type I interferon production and targeting ubiquitinated IRF3 for autophagic degradation. In response to oxidative stress, promotes an increase in SQSTM1 levels, phosphorylation, and body formation by preventing its autophagic degradation (By similarity). In turn, activates the KEAP1-NRF2/NFE2L2 antioxidant pathway (By similarity). Also plays non-autophagy role by mediating the shuttle of IL-12 to late endosome for subsequent secretion (By similarity).
Synonyms: KIAA0049; M17S2; MIG19; CA125; 1A1-3B; IAI3B
Tractability: PROTAC: UniProt records ubiquitination sites on it; ubiquitination databases record sites on it; its protein half-life has been measured.
Gene: Protein-coding gene on chromosome 17 (43,170,317 to 43,211,689, forward strand). Ensembl gene ENSG00000188554.
Subcellular location: Cytoplasm; Cytoplasmic vesicle, autophagosome; Lysosome; Cytoplasm, myofibril, sarcomere, M line
Subcellular location (Human Protein Atlas): Vesicles; Cytosol; Nuclear bodies; Nucleoplasm
Pathways (Reactome):
Autophagy: Pexophagy
Gene Ontology:
Molecular function: protein binding; ubiquitin binding; mitogen-activated protein kinase binding; zinc ion binding
Biological process: macroautophagy; negative regulation of osteoblast differentiation; regulation of bone mineralization; regulation of stress-activated MAPK cascade
Cellular component: cytoplasm; cytosol; lysosome; membrane; mitochondrion; receptor complex; autophagosome; late endosome; peroxisomal membrane; phagophore assembly site; M band; mitochondrial intermembrane space
Genetic constraint (gnomAD): Loss-of-function variants: 45 observed, 86.52 expected, observed/expected ratio (o/e) 0.52, 90% interval 0.41 to 0.67. The upper end of that interval is the gene's LOEUF score, 0.67, which puts it in group 2 of 6, group 1 being the genes least tolerant of losing a copy. Missense variants: 891 observed, 1,004.5 expected, observed/expected ratio (o/e) 0.89, 90% interval 0.84 to 0.94. Synonymous variants: 332 observed, 370.65 expected, observed/expected ratio (o/e) 0.9, 90% interval 0.82 to 0.98.
Homologues: Orthologues: chimpanzee NBR1 (98% identical), macaque NBR1 (96% identical), pig NBR1 (89% identical), rabbit NBR1 (89% identical), dog NBR1 (87% identical), mouse Nbr1 (85% identical), rat Nbr1 (84% identical), guinea pig NBR1 (69% identical), tropical clawed frog nbr1 (47% identical), zebrafish nbr1b (42% identical), zebrafish nbr1a (38% identical).
Diseases named in the same sentence as NBR1 in open-access papers:
NBR1 is named in the same sentence as 56 diseases in open-access papers, as found by Europe PMC text mining. Sharing a sentence is not in itself a finding about the gene and the disease. The quoted sentences say what the papers report.
breast cancer (11 papers, 2018 to 2026). A primary or metastatic malignant neoplasm involving the breast. "In addition, genetic inhibition of autophagy in breast cancer increases metastasis to the lung and disseminated tumor cells cause overgrowth to overt macrometastasis; this is explained by the intracellular deposition of autophagy receptor, NBR1." (PMID 36831154, 2023). "Further, autophagy has been reported to suppress breast cancer metastasis by degrading the neighbor of BRCA1 gene 1 (NBR1)." (PMID 38431606, 2024). "In HRAS-transformed MCF10A breast cancer cells, which model early tumor progression, NBR1 interacts with ubiquitinated FA proteins, facilitating their degradation through autophagy." (PMID 39596452, 2024). "In human urothelial cancer cells, NBR1 shows high expression, and NBR1 is widely involved in the migration and development of various tumors, such as breast cancer and pancreatic cancer." (PMID 37889013, 2023). "Accordingly, recent studies have demonstrated that NBR1 plays an important role in breast cancer metastatic progression." (PMID 33634029, 2020). "Moreover, even dysfunctional autophagy can be pathogenic, as cytosolic accumulation of the selective receptor NBR1 drives breast cancer metastasis." (PMID 41592105, 2026). "Decreasing NBR1 levels impairs FA turnover, reducing breast cancer cell migration." (PMID 39596452, 2024). "Indeed, in Ras-transformed breast cancer cells, focal adhesion turnover is mediated by autophagy and is dependent on the autophagy receptor NBR1." (PMID 40396018, 2022). "Interestingly, a recent report involves another autophagy cargo protein, namely NBR1, in breast cancer metastatic dissemination." (PMID 32714931, 2020). "By using different mammary cancer mouse models, the authors show that although genetic ablation of autophagy attenuates primary tumor growth, eventually fuels metastatic outgrowth and that NBR1 plays a key role in this context." (PMID 32714931, 2020). "Interestingly, ectopic NBR1 overexpression in breast cancer cells is sufficient to promote metastatic outgrowth." (PMID 33634029, 2020). "Nbr1 also promotes cell migration and regulates focal adhesion in a breast cancer cell line." (PMID 30250843, 2018). "Furthermore, Nbr1 transcript levels are highly decreased in mammary cancer cell lines compared to their healthy counterparts." (PMID 30250843, 2018). "However, autophagy also suppresses breast cancer metastasis by degrading NBR1." (PMID 35383175, 2022). "Intracellular accumulation of NBR1 is also involved in prometastatic differentiation that induces aggressive basal differentiation such as cytokeratin 14 and TP63 in breast cancer." (PMID 36831154, 2023). "Intracellular accumulation of NBR1 is also involved in prometastatic differentiation; it induces aggressive basal differentiation through the expression of cytokeratin 14 and TP63 in breast cancer." (PMID 36831154, 2023). "For instance, in a cellular model of breast cancer cell known as HRAS-transformed MCF10A cells that mimic an early stage of the tumor progression cascade, NBR1 binds ubiquitylated proteins of FAs mediating their degradation by autophagy." (PMID 33634029, 2020). "Indeed, reduction of NBR1 levels reduces FAs turnover with a negative impact in breast cancer cell migration." (PMID 33634029, 2020).
pancreatic cancer (10 papers, 2021 to 2025). "It has been reported that MHC-1 molecule was degraded through NBR1-mediated selective autophagy in glioma and pancreatic cancer, which was considered as the major cause of immune escape." (PMID 40410130, 2025). "MHC-1 molecule has been reported to degrade through NBR1-mediated selective autophagy to enhance the tumor cells escaped from CTLs in glioma and pancreatic cancer." (PMID 40410130, 2025). "In pancreatic cancer cells, excessive autophagy facilitated by NBR1 contributes to immune evasion through the autophagic degradation of MHC-I." (PMID 38169523, 2024). "A recent study shows that NBR1 binds to MHC-I through its ubiquitin-binding domain and mediates the degradation of MHC-I molecules in autophagy lysosomes, thereby promoting immune evasion of pancreatic cancer." (PMID 37915049, 2023). "However, the knockdown of NBR1, which is involved in MHC-Ι down-regulation in pancreatic cancer cells, did not exert any effect, excluding NBR1 as a receptor for ORF8-mediated MHC-Ι degradation." (PMID 34021074, 2021).
viral infection (9 papers, 2020 to 2024). "It was demonstrated that overexpression of NBR1 stimulates TuMV replication, while its deficiency inhibits virus infection." (PMID 37636115, 2023). "TuMV‐encoded 6K2 protein triggers the UPR, which activates the NBR1‐mediated selective autophagy to help viral infection and accumulation." (PMID 34897936, 2022). "Pull-down analysis indicated that GST-PB1 directly interacted with His-NBR1, and Endogenous co-IP experiments indicated that SZ19 PB1 physiologically associated with NBR1 following SZ19 virus infection." (PMID 33577621, 2021). "For instance, in the context of viral infections, NBR1 plays a role in reducing the production of type I interferon by degrading IRF3 through autophagy, thereby assisting in the attenuation of the inflammatory response." (PMID 38169523, 2024). "Amongst these autophagy receptors, NBR1 (neighbor of BRCA1), a ubiquitin-binding scaffold protein, increases in viral infections, and NBR1 accumulates and is abnormal in IBM muscle." (PMID 38693436, 2024). "The expression of LC3-II, p62, and NBR1 slightly increased in Baf-A1-treated cells after infection with HEP-Flury compared to uninfected, indicating that autophagy was further induced after viral infection, while autophagy substrates were also accumulating." (PMID 34113320, 2021).
clear cell renal cell carcinoma (4 papers, 2017 to 2022). "Decreased NBR1 mRNA level is associated with a poor clinical outcome in patients with clear cell renal carcinoma, indicating NBR1 mRNA level is negatively related with the prognosis of cancer patients." (PMID 34926299, 2021). "Lower levels of neighbor of BRCA 1 (NBR1) expression is associated with poorer prognosis of clear cell renal cell carcinoma." (PMID 33600074, 2021). "NBR1 is closely related to renal cancer, and also participates in regulation of the autophagy pathway in renal clear cell cancer." (PMID 36465646, 2022). "And there is a positive correlation between NBR1 and BRCA1 expression in clear cell renal cell carcinoma in supplementary (R = 0.355, p < 0.0001)." (PMID 29212269, 2017).
ovarian carcinoma (4 papers, 2013 to 2021). A malignant neoplasm originating from the surface ovarian epithelium. "NBR1 is originally cloned as a candidate gene for the ovarian cancer antigen and its position close to BRCA1, two isoforms of NBR1A and NBR1B are downregulated in malignant mammary tissues when compaired with normal cells." (PMID 29212269, 2017). "Neighbor of Brca1 gene (NBR1) has been of interest due to its position close to BRCA1, but has no involvement in breast or ovarian cancer." (PMID 29212269, 2017). "A deletion affecting BRCA1, NBR1, and NBR2 at 17q21.31 was identified in a patient with hormone receptor-negative BC with a family history of ovarian cancer (family 252)." (PMID 23967248, 2013).
renal carcinoma (3 papers, 2017 to 2022). A carcinoma arising from the epithelium of the renal parenchyma or the renal pelvis. "The overexpression of truncated NBR1 increases the proliferation capacity of renal cancer cells compared with cells overexpressing WT NBR1." (PMID 36255390, 2022). "In conclusion, our results provide the idea that NBR1 is downregulated in ccRCC tissues, renal cancer cell lines and their sunitinib-resistant cells and identified as an new independent predictor for prognosis in ccRCC patients." (PMID 29212269, 2017). "We screened the NBR1 mRNA in ccRCC from The Cancer Genome Atlas (TCGA) database and examined expression levels of NBR1 mRNA in 48 cases of ccRCC tissues, renal cancer cell lines and chemoresistance cells by qRT-PCR." (PMID 29212269, 2017). "In the present study, NBR1 was downregulated in ccRCC tissues, renal cancer cell lines and their chemoresistance cells." (PMID 29212269, 2017). "In this study, NBR1 was downregulated in ccRCC tissues, renal cancer cell lines and their sunitinib-resistant cells." (PMID 29212269, 2017).
Alzheimer disease (2 papers, 2021 to 2025). A progressive, neurodegenerative disease characterized by loss of function and death of nerve cells in several areas of the brain leading to loss of cognitive function such as memory and language. "The analysis based on the SC2disease database also indicates that Dph3 and Nbr1 are associated with Alzheimer's disease." (PMID 39912396, 2025).
depression (2 papers, 2022 to 2025). "In summary, NBR1 can improve oxidative stress levels and depression-like behavior in vivo through autophagy, and it is likely to be a potential target for the treatment of depression." (PMID 40497971, 2025). "Analyzing the protein regulatory network of FEZ1, in a series of interaction proteins obtained, it is found that the three autophagy-related proteins SCOC, ULK1, and NBR1 might play a role in depression." (PMID 35435132, 2022).
glioma (2 papers, 2023 to 2025). A benign or malignant brain and spinal cord tumor that arises from glial cells (astrocytes, oligodendrocytes, ependymal cells). "To verify that LINC01232 promotes glioma immune escape by regulating NBR1, we knocked down NBR1 in the glioma cell lines U‐87MG and U‐251 while overexpressing LINC01232." (PMID 37097629, 2023). "This study reveals the existence of critical molecular crosstalk between TAMs and glioma mediates through the LINC01232/E2F2/NBR1/MHC‐I axis to support malignant tumor growth, indicating that targeting this axis may have therapeutic potential." (PMID 37097629, 2023). "The LINC01232/E2F2/NBR1/MHC‐I expression levels among normal brain tissues (NBT), low‐grade glioma tissues (LGG), and high‐grade glioma tissues (HGG) were compared." (PMID 37097629, 2023). "In addition, ELISA results indicated that CD8+ T‐cell supernatants cocultured with LINC01232‐OE glioma cells showed lower levels of IFN‐γ, TNF‐α, and Gzmb secretion; however, knocking down NBR1 while overexpressing LINC01232 could also reverse this phenomenon." (PMID 37097629, 2023). "Flow cytometry and real‐time quantitative PCR results indicated that CD8+ T cells cocultured with LINC01232‐OE glioma cells showed lower proliferation and expression of IFN‐γ, TNF‐α, and Gzmb; however, knocking down NBR1 while overexpressing LINC01232 could reverse this phenomenon." (PMID 37097629, 2023).
hepatocellular carcinoma (2 papers, 2021 to 2025). A malignant tumor that arises from hepatocytes. "p62 and NBR1 have also been recently reported to play opposing roles in regulation of STING and interferon signaling in hepatic stellate cells and hepatocellular carcinoma phenotypes." (PMID 40568100, 2025). "Another study has also reported that NBR1 knockdown could not restore peroxisome numbers in hepatoma-derived Huh7 cells under hypoxia-induced peroxisome degradation." (PMID 34360754, 2021).
Obesity (2 papers, 2015 to 2021). Accumulation of substantial excess body fat. "Here we show that whole-body and adipocyte-specific ablation of NBR1 reverts the obesity phenotype induced by p62 deficiency by restoring global energy expenditure and thermogenesis in brown adipose tissue." (PMID 34001883, 2021). "We demonstrate that upon p62 inactivation, NBR1 represses the activity of PPARγ, establishing an unexplored p62/NBR1-mediated paradigm in adipocyte thermogenesis that is critical for the control of obesity." (PMID 34001883, 2021). "Recently, it hase been shown that the PB1 domain-containing adaptor NBR1 functions as an organizer of MEKK3/MKK4, the activators of JNK, in macrophages to regulate JNK activation, ATM M1 activation and adipsoe tissue inflammation in obesity." (PMID 25816341, 2015).
renal cell carcinoma (2 papers, 2022 to 2025). "Recently, whole exome sequencing on germline DNA from a family presenting with different subtypes of renal cell carcinoma (RCC) identified a frameshift mutation in NBR1." (PMID 36255390, 2022).
synucleinopathies (2 papers, 2016 to 2022). "This role of p62 can be extended to other protein aggregation disease models such as α-synucleinopathy, where interdependency of p62 and NBR1 expressions in aggregate formation process was reported." (PMID 27526095, 2016).
bladder cancer (1 paper, 2020). "Recently, we reported that an mTOR inhibitor induced the initiation of autophagy, but it was not adequate to enhance cell death, owing to the protective effect of NBR1, an antioxidant-related gene, in bladder cancer cells." (PMID 33302414, 2020).
Burkholderia Infections (1 paper, 2019). Infections with bacteria of the genus BURKHOLDERIA. "In this study, we have characterized the consequence of a host key cargo adaptor protein, p62/NBR1, associated with autophagic flux with Burkholderia infection which initially identified as a bridge between LC3 and polyubiquitylated protein aggregates destined for autophagic removal." (PMID 30569531, 2019).
Cerebral ischemia (1 paper, 2025). Restriction of arterial blood supply to the brain associated with insufficient oxygenation to support the metabolic requirements of the tissue. "Moreover, Tat-NTS—a related peptide—protects against cerebral ischemia/reperfusion injury by enhancing SUMOylation of ANXA1, thereby promoting NBR1-dependent selective autophagic degradation of IKKα, suppressing NF-κB activation, and reducing IL-1β and TNF-α release in microglia." (PMID 41007413, 2025).
cholangiocarcinoma (1 paper, 2020). A carcinoma that arises from the intrahepatic biliary tree (intrahepatic cholangiocarcinoma) or from the junction, or adjacent to the junction, of the right and left hepatic ducts (hilar cholangiocarcinoma). "These antecedents suggest that NBR1 could be implicated in the degradation of ciliary component through selective autophagy, explaining the loss of the primary cilium in cholangiocarcinoma." (PMID 33634029, 2020). "In addition, silencing of NBR1 in HuCCT1 cells, a cell line of cholangiocarcinoma, increases the size of the primary cilia." (PMID 33634029, 2020).
colitis (1 paper, 2022). Inflammation of the colon. "In myeloid cells, the absence of ATG5 will shunt selective autophagy receptor NBR1 to target IL-12 to late endosomes for secretion, thus instigating inflammation in a murine colitis model." (PMID 37425656, 2022).
inclusion body myositis (1 paper, 2012). A slowly progressive degenerative inflammatory disorder of skeletal muscles characterized by late onset weakness of specific muscles and distinctive histopathological features. "NBR1 also colocalizes with p62, LC3, and phosphorylated tau in ubiquitinated protein aggregates of sporadic inclusion-body myositis (s-IBM) that is the most common degenerative myopathy associated with aging." (PMID 22518139, 2012).
intervertebral disc degeneration (1 paper, 2024). "In this study, we present, for the first time, the significant role of selective autophagy receptor NBR1 in regulating senescence of NPCs and intervertebral disc degeneration." (PMID 38169523, 2024). "Therefore, we wondered whether NBR1 inhibits intervertebral disc degeneration by retarding cellular senescence of NPCs." (PMID 38169523, 2024).
leprosy (1 paper, 2017). Leprosy is a chronic infectious disease affecting primarily the skin and peripheral nervous system. "Dialyzed proteins from leprosy skin biopsies were evaluated by commercial ELISA assays for SQSTM1/p62 and NBR1." (PMID 28056107, 2017).
leptospirosis (1 paper, 2020). A contagious bacterial infection caused by spirochetes of the genus Leptospira. "We analysed the key autophagy components p62/NBR1 in PBMCs from meliodosis patients, healthy controls in addition to B. pseudomallei-negative sepsis and melioidosis-negative suspected leptospirosis controls." (PMID 32815800, 2020). "Although very low levels of p62 were observed in meliodoisis-negative B. pseudomallei sepsis and suspected leptospirosis patients, the NBR1 levels were distinctly statistically significant." (PMID 32815800, 2020). "Similar to p62, cytosolic NBR1 had significantly higher levels (fivefold) in confirmed, as well as probable, cases of melioidosis than in healthy controls, or meliodoisis-negative sepsis or meliodoisis-negative suspected leptospirosis categories." (PMID 32815800, 2020).
muscular atrophy (1 paper, 2017). The loss of muscle tissue due to inactivity or disease. "Rapid upregulation after denervation of several E3 ligases and autophagy-related proteins, including NBR1 and sequestosome-1, indicates that M-band proteins are most likely to be the first proteins targeted for breakdown during muscular atrophy." (PMID 28546288, 2017).